ATP5F1EP2 (ATP synthase F1 subunit epsilon pseudogene 2)
Description:
Mitochondrial membrane ATP synthase (F(1)F(0) ATP synthase or Complex V) produces ATP from ADP in the presence of a proton gradient across the membrane which is generated by electron transport complexes of the respiratory chain. F-type ATPases consist of two structural domains, F(1) - containing the extramembraneous catalytic core, and F(0) - containing the membrane proton channel, linked together by a central stalk and a peripheral stalk. During catalysis, ATP synthesis in the catalytic domain of F(1) is coupled via a rotary mechanism of the central stalk subunits to proton translocation. Part of the complex F(1) domain and of the central stalk which is part of the complex rotary element. Rotation of the central stalk against the surrounding alpha(3)beta(3) subunits leads to hydrolysis of ATP in three separate catalytic sites on the beta subunits (By similarity).
Synonyms: formerly ATP5EP2
Gene: Processed pseudogene on chromosome 13 (27,945,260 to 27,945,415, forward strand). Ensembl gene ENSG00000180389.
Subcellular location: Mitochondrion inner membrane
Diseases named in the same sentence as ATP5F1EP2 in open-access papers:
ATP5F1EP2 is named in the same sentence as 2 diseases in open-access papers, as found by Europe PMC text mining. Sharing a sentence is not in itself a finding about the gene and the disease.
ATP5F1EP2 shares sentences with these, for which no sentence is quoted: cancer (1 paper); tumor (1).